IGF1 (insulin like growth factor 1)
Diseases named in the same sentence as IGF1 in open-access papers (continued):
Sharing a sentence is not in itself a finding about the gene and the disease.
fibrosis (40 papers, 2014 to 2026). the formation of excess fibrous connective tissue in an organ or tissue in a reparative or reactive process. "Taken together, these results suggested that IGF-1 inhibited AngII-induced cardiac fibrosis through Akt-dependent and ROCK2- associated pathways." (PMID 34244467, 2021). "Moreover, IGF-1 might associate with a fibrosis-specific serum metabolite profile, where many bile acids were found increased in advanced fibrosis, namely, cholic acid, which also correlated with serum IGF-1." (PMID 34249975, 2021). "Further evaluation and validation allowed us to identify IGF1 as a potential immune-related critical gene for pulmonary vascular remodeling and fibrosis." (PMID 37731513, 2023). "Activated AT2 cells continue to secrete TGF-β, PDGF, and IGF-1 to promote interstitial and intraalveolar fibrosis, which restrict lung capacity." (PMID 35913450, 2022). "By establishing a cutoff value of IGF-1 inferior to 98.83 ng/ml for the presence of advanced fibrosis, 70% sensitivity, 61% specificity, and 63% overall accuracy were obtained." (PMID 34249975, 2021). "So we further explore the expression profile of atrial transcripts in AF, and illustrate the role of IGF1 in atrial fibrosis, which is expected to provide a new explanation for the pathogenesis of AF, and provide a new strategy for the prevention of AF." (PMID 30770724, 2019). "IGF-1 expression by interstitial macrophages was found to correspond positively to the level of fibrosis in IPF patients." (PMID 27677175, 2016). "Insulin-like growth factor 1 (IGF-1), implicated as a potent, pro-fibrotic, fibroblast growth factor in the context of IPF and bleomycin-induced fibrosis, was increased in the BLEO group, and reduced in the BLEO+EX group." (PMID 27677175, 2016). "Limited data show that low insulin-like growth factor-1 (IGF-1) concentrations may contribute to hepatic fibrosis by acting on hepatic stellate cells." (PMID 41708551, 2026). "IGF-1 plays a double-edged role in mucosal healing and repair, but its regulatory mechanism in intestinal fibrosis remains unclear and needs further research." (PMID 40862456, 2025). "Finally, the disease gene-association analysis on the DEGs without the respiratory tract disease filter showed that six DEGs (namely, ACTG2, AGER, COL1A1, COL3A1, IGF1, and SPP1) were associated with fibrosis." (PMID 39944354, 2024). "Moreover, 26 specific serum metabolites were able to distinguish advanced fibrosis, with several bile acids increased in advanced fibrosis, and both cholic acid and PC (17:0/18:2) positively correlated with IGF-1." (PMID 34249975, 2021). "The findings that serum IGF-1 levels in patients with chronic hepatitis C negatively correlated with histologic fibrosis score and improved during anti-viral therapy may support this hypothesis." (PMID 24595361, 2014). "In the studied population, the total IGF-1/intact IGFBP-3 ratio remained significantly lower in individuals with fibrosis than in controls with milder or no histologic lesions in the liver (p = 0.04)." (PMID 36831184, 2023). "Lastly, the performance of the proposed biomarker panels comprising serum adiponectin and lipids for NAFL vs. NASH stratification and serum IGF-1 with INR and ferritin for identification of advanced fibrosis should be prospectively tested in a different cohort." (PMID 34249975, 2021). "On the other hand, a 10 day-IGF-1 replacement therapy returned hemodynamic values and fibrosis to normality, albeit not all genes returned to normal values." (PMID 28806738, 2017). "The increased mRNA and protein expression of cytokines, such as TGF-β1 and insulin-like growth factor 1 (IGF-1), in all intestinal layers coincident with the inflammation sites and the increased deposition of ECM proteins synthesized by myofibroblasts induce intestinal fibrosis." (PMID 35222098, 2022).
fibrosis (continued). "However, by combining serum IGF-1, ferritin, and INR, the discriminatory power was significantly improved, resulting in AUROC value of 0.81 and overall accuracy of 93%, considering the ~10% prevalence of advanced fibrosis in this cohort." (PMID 34249975, 2021). "Hence, an effect of IGF-1 against UUO-induced renal injury and fibrosis was confirmed." (PMID 27301852, 2016).
myopia (40 papers, 2008 to 2025). "Insulin and insulin-like growth factor-1 (IGF-1) are implicated in both myopia progression and MetS, providing a potential biological basis for their association." (PMID 40076793, 2025). "In a cohort of 1,160 children and adolescents (ages 2–17), IGF1 rs5742714 was linked to myopia in children under 6, while FGF10 rs339501 was associated with moderate and mild myopia in children aged 6–1215." (PMID 40410244, 2025). "Expression of IGF-1 rs6214, GA and AA genotypes, and A minor allele were significantly higher in high myopia patients than in the control group." (PMID 39597899, 2024). "Juvenile-onset myopia caused by increased vitreal chamber growth is another IGF-1-induced condition also related to increased height and BMI during adolescence." (PMID 36729355, 2023). "The IGF1 gene also is located within the myopia-associated MYP3 interval, which has been mapped using the linkage disequilibrium method." (PMID 35862416, 2022). "In conclusion, this meta-analysis suggests that the G allele of the IGF1 rs2162679 SNP is a potential protective factor for any myopia, which is worth further researches." (PMID 35862416, 2022). "In this study, our meta-analysis shows there is association between IGF1 rs2162679 and any myopia in codominant model (GA vs. AA) and dominant model (GG+GA vs. AA)." (PMID 35862416, 2022). "Meta-analysis of updated data reveals that the G allele of the IGF1 rs2162679 SNP is a potential protective factor for any myopia, which is worth further researches." (PMID 35862416, 2022). "The associations between two SNPs of IGF-1 (rs10860860 and rs2946834) and high myopia (P < 0.05) have been indicated to be significant in a Polish population." (PMID 35647299, 2022). "It is shown that the potential association between IGF-1 polymorphisms and myopia has been investigated in a recent study." (PMID 35647299, 2022). "Genetic association studies showed that single nucleotide polymorphism observed in IGF-1 was significantly associated with different types of myopia, including high myopia in Caucasian and Chinese populations." (PMID 34713181, 2021). "This study investigated the association between the SNP rs2162679 in the intron of IGF1 and myopia in a young Chinese population during puberty and pre-puberty." (PMID 32025377, 2020). "Genetic studies have been used to genotype the single-nucleotide polymorphisms of IGF1 and have shown that it is significantly associated with high or extreme myopia in Caucasian and Chinese populations." (PMID 32025377, 2020). "Here, we aimed to show that genetic variants of IGF1 contributed to the development of myopia in a young Chinese Han population." (PMID 32025377, 2020). "Prior researches in China also illustrated that IGF-1 rs12423791 was significantly associated with high myopia in Chinese populations." (PMID 26076017, 2015). "Recently, a single nucleotide polymorphism (SNP) in IGF-1 was reported to be associated with several types of myopia, including high myopia, in Caucasians." (PMID 23734076, 2013). "Given that the previous studies included refractive myopia cases, of which only a proportion are axial myopia, we infer that they lack the power to rigorously test the association between IGF-1 SNPs and axial myopia." (PMID 23734076, 2013). "Second, we did not trace the method of Mak’s study, which showed a significant association of IGF-1 haplotypes with refractive high myopia." (PMID 23734076, 2013). "In the present study, we conducted a systematic case-control study to validate the association between polymorphisms of the IGF-1 gene and high and extreme myopia, using a large cohort of 2,867 unrelated Japanese individuals." (PMID 23734076, 2013). "In a recent study, IGF-1 polymorphisms were tested for possible association with myopia, and the SNP rs6214 showed significant association with the high-grade and any-myopia phenotypes." (PMID 22509095, 2012).
myopia (continued). "Among 7 IGF-1 SNPs tested, three SNPs–rs5742629, rs12423791, and rs1457601–showed significant (p<0.05) differences in allele frequencies between the high myopia and control groups (p=0.021, p=0.024, p=0.040, respectively)." (PMID 22509095, 2012). "Recent work has suggested that insulin-like growth factor 1 (IGF-1) gene polymorphisms are genetically linked with high-grade myopia (HM), which is a complex-trait eye disorder in which numerous candidate loci and genes are thought to play a role." (PMID 21976954, 2011). "Both Family-Based Association Test (FBAT) and family-based Pedigree Disequilibrium Test (PDT) were used to examine the potential association of the IGF-1 SNPs rs6214, rs10860860, and rs2946834 with HM or any myopia." (PMID 21976954, 2011). "In the present study, we tested the association of rs6214, rs10860860, and rs2946834 in the IGF-1 gene with HM and any myopia phenotype in 42 Polish families." (PMID 21976954, 2011). "Furthermore, a recent meta-analysis has demonstrated that the G allele of the IGF1 rs2162679 SNP is a potential protective factor for any myopia." (PMID 38203671, 2023). "rs2162679 in IGF-1 was associated with myopia in a young Chinese population." (PMID 35647299, 2022). "Therefore, we present herein an updated systematic review and meta-analysis to evaluate the potential association between IGF1 SNPs and any myopia." (PMID 35862416, 2022). "The insulin-like growth factor 1 (IGF1) gene is located within the myopia-associated MYP3 interval, which suggests it may play an important role in the progression of myopia." (PMID 35862416, 2022). "In anther word, individuals with G allele in rs2162679 of IGF1 have less chance of getting myopia." (PMID 32025377, 2020). "These genetic variants in IGF1 may be related to the onset or early development of myopia in young populations." (PMID 32025377, 2020). "The SNP rs2162679 in IGF1 was associated with myopia in a young Chinese population." (PMID 32025377, 2020). "Additionally, none of the individual studies significantly affected the association between IGF-1 rs12423791 and high myopia, according to sensitivity analysis." (PMID 26076017, 2015). "The IGF-1 gene is located at a well replicated myopia susceptibility locus, MYP3." (PMID 23734076, 2013). "In humans, although a significant association of the IGF-1 SNP with any myopia and with high myopia was reported in Caucasians in 2010, the association was not confirmed in a Polish family cohort, using the single-SNP association, family-based association, and pedigree disequilibrium tests." (PMID 23734076, 2013). "Furthermore, two subsequent Chinese studies showed a significant association of IGF-1 tag SNPs with high or extreme myopia." (PMID 23734076, 2013). "Hence, it seems futile to evaluate minor SNPs when testing the association of IGF-1 SNPs with high myopia." (PMID 23734076, 2013). "Genetic evidence supporting a role for IGF-1 in myopia has come from analysis of a large Caucasian cohort where the single nucleotide polymorphisms (SNPs) were significantly associated with high myopia." (PMID 22509095, 2012). "In this study, we found that IGF-1 polymorphism may be associated with extreme myopia in the Chinese population and should be investigated further." (PMID 22509095, 2012). "The polymorphism of rs12423791 in IGF-1 may be associated with extreme myopia in the Chinese population and should be investigated further." (PMID 22509095, 2012). "Interestingly, a very recent study demonstrated a genetic association between IGF-1 and high-grade myopia in an international family cohort." (PMID 21655358, 2011). "However, the association between IGF1 SNPs and any myopia is rarely reported." (PMID 35862416, 2022).
myopia (continued). "Nevertheless, all previous studies focused on the relationship between single-nucleotide polymorphisms (SNPs) in IGF1 and high myopia, whilst the association of SNP in IGF1 with mild or moderate myopia, which usually occurs during puberty and pre-puberty, remains unknown." (PMID 32025377, 2020). "Therefore, we performed a meta-analysis to examine whether there is such an association and to produce a reliable estimate of the association between IGF-1 gene rs12423791 and rs6214 polymorphisms and high myopia." (PMID 26076017, 2015). "Elevated insulin levels in the bloodstream trigger the secretion of insulin-like growth factor 1 (IGF-1), which influences cell growth and differentiation, ultimately leading to axial elongation of the eyeball and the development of myopia." (PMID 39408299, 2024). "Nine studies involving 4596 subjects with any myopia and 4950 controls examined 25 SNPs in IGF1 gene, among which seven SNPs were included in this meta-analysis." (PMID 35862416, 2022). "Polymorphism of insulin-like growth factor-1 (IGF-1), a downstream production of insulin, also is associated with severe myopia." (PMID 35652067, 2022). "IGF-1 has been listed as a potential myopia-related gene in animal experiments and in-body research and is considered to play an important role in controlling eyeball growth." (PMID 35647299, 2022). "Insulin-like growth factor-1 and vasoactive intestinal peptide also play a significant role in myopia." (PMID 36418970, 2022). "The study sought to investigate the effect of the Insulin-like growth factor-1 (IGF-1) and Matrix metalloproteinase-9 (MMP-9) genes polymorphisms on high myopia in a Han population of China." (PMID 35647299, 2022). "Together, these studies suggest the important role of IGF-1 in ocular growth and in the progression of myopia." (PMID 34713181, 2021). "The secretion of TIMP-1, MMP2, bFGF, and IGF-1, which were involved in pathological myopia, were detected with ELISA assay in ARPE-19 cells treated with 1 μg/mL of insulin for 24 or 72 h." (PMID 34001063, 2021). "Growth factors such as IGF-1 released by eye exercise were selected as one of the key NHFs for SAT-001 to control the progression of myopia." (PMID 34713181, 2021). "Recent genetic studies suggested that IGF-1 should be evaluated with caution as a candidate gene for myopia." (PMID 31781378, 2019). "In the current study we investigated the association of three myopia-associated genes, GJD2, IGF1, and HGF, and their interaction with eye biometric parameters in two Chinese cohorts." (PMID 22509107, 2012). "The insulin-like growth factor 1 (IGF1) gene within the myopia 3 (high grade, autosomal dominant, MYP3) locus, has been reported to be associated with myopia in Caucasians." (PMID 22509107, 2012). "Our results do not support recent studies reporting an association of the SNPs rs6214, rs10860860, and rs2946834 in the IGF-1 gene with HM and any myopia phenotypes." (PMID 21976954, 2011). "Further replication studies involving other populations are needed to investigate the possible role of IGF-1 as a potential myopia candidate gene." (PMID 21976954, 2011). "In the present study, we investigated the previously reported association of the SNPs rs6214, rs10860860, and rs2946834 in the IGF-1 gene with familial HM or any myopia phenotypes." (PMID 21976954, 2011). "The chick model of experimental myopia suggests a possible role for IGF-1 in eye growth and elongation; and therefore, in myopia development and progression." (PMID 21976954, 2011). "Previous studies have shown that IGF1 contributes to eye growth as well as myopia development, and, in fact, the IGF-1 gene on chromosome 12q23.2 is located within the high-grade myopia locus, MYP3 interval, which has been mapped for autosomal dominant high myopia." (PMID 38203671, 2023). "Main results of the pooled ORs between IGF1 SNPs and any myopia." (PMID 35862416, 2022).
myopia (continued). "Furthermore, an increase in blood insulin levels is known to promote the secretion of Insulin-like growth factor 1 (IGF-1), which promotes cell growth and differentiation, leading to the axial elongation characteristic of myopia in the eye." (PMID 35333875, 2022). "SNP rs2162679 of IGF1 has been reported to be associated with several kinds of cancer, which reminds us that IGF1 SNPs might play similar role in the onset or progesssion of myopia and cancer." (PMID 35862416, 2022). "Based on results from animal and clinical studies, certain neuronal–humoral factors (NHFs), such as IGF-1, dopamine, and cortisol may be involved in the progression of pediatric myopia." (PMID 34713181, 2021). "Additionally, treatment of post-embryonic chicken eyes with IGF-1 (along with FGF2) is sufficient to induce excessive ocular growth, in part due to stimulated proliferation of CMZ cells, ultimately causing extreme myopia." (PMID 34207050, 2021). "This may explain why IGF-1 resulted in extreme increases in axial length in chicks but has only been related to mild to moderate myopia in humans." (PMID 32025377, 2020). "The results demonstrated that the significant association was not present in any genetic models between IGF-1 rs12423791 or rs6214 and high myopia." (PMID 26076017, 2015). "IGF-1 was identified as a high myopia-related protein in two animal model studies." (PMID 23734076, 2013). "The haplotype analysis with a variable-sized sliding-window strategy also showed a lack of association of IGF-1 SNPs with high or extreme myopia." (PMID 23734076, 2013). "The results of the present study using a Japanese subset do not support the proposal that the IGF-1 gene determines susceptibility to high or extreme myopia in Caucasians and Chinese." (PMID 23734076, 2013). "However, although the original study evaluated a total of 13 tagging SNPs that showed a MAF ≥5% in the IGF-1 gene, the study reported that only rs6214, whose MAF is 42%, showed a significant association with high myopia." (PMID 23734076, 2013). "In summary, we showed that none of the major tagging SNPs of IGF-1 were associated with high and extreme myopia in a large cohort of Japanese subjects." (PMID 23734076, 2013). "Haplotype analysis of IGF-1 in extreme myopia and control subjects." (PMID 22509095, 2012). "Haplotype analysis of the IGF-1 gene in high myopia and control subjects." (PMID 22509095, 2012). "The association of IGF1 with lens thickness but not with other ocular dimensions, constellated with the existing genetic association of IGF1 with myopia, possibly implicated its specific role in refractive myopia." (PMID 22509107, 2012). "Again, the FBAT and PDT analyses showed no positive association between the IGF-1 SNPs rs6214, rs10860860, and rs2946834 and any myopia phenotype." (PMID 21976954, 2011). "Several lines of evidence support a role of insulin and/or IGF-1 in the control of eye growth, including one strong clue coming from chicken studies, in which it was shown that intravitreal injections of both peptides lead to the development of myopia." (PMID 21655358, 2011). "Additionally, increased incidence of single nucleotide polymorphism (SNP)s association between the insulin-like growth factor 1 (IGF-1) gene and high-grade myopia, and polymorphisms in the promoter regions of matrix metalloproteinase (MMP) genes were reported." (PMID 21850178, 2011). "Interestingly, patients with primary growth hormone insensitivity who received IGF-1 therapy showed a tendency toward mild myopia." (PMID 21655358, 2011). "Insulin-like growth factor-1 (IGF-1) may be involved in myopia." (PMID 40735444, 2025). "This suggests that IGF1 may play an important role in the progression of myopia." (PMID 35862416, 2022).